Y_RNA (Y RNA )
Gene: Miscellaneous RNA gene on chromosome 1 (153,726,252 to 153,726,353, reverse strand). Ensembl gene ENSG00000199565.
Homologues: Orthologues: chimpanzee Y_RNA (99% identical), macaque Y_RNA (96% identical), dog Y_RNA (81% identical), pig Y_RNA (79% identical). Paralogues in human: RNY3 (93% identical), Y_RNA (91% identical), RNY3P1 (90% identical), Y_RNA (90% identical), Y_RNA (89% identical), Y_RNA (88% identical), Y_RNA (87% identical), Y_RNA (86% identical), RNY3P11 (85% identical), RNY3P14 (85% identical), RNY3P16 (85% identical), Y_RNA (85% identical), and 98 more.